BRINP3 (BMP/retinoic acid inducible neural specific 3)
Description:
Inhibits neuronal cell proliferation by negative regulation of the cell cycle transition. Promotes pituitary gonadotrope cell proliferation, migration and invasion, when overexpressed. May play a role in cell pituitary tumor development.
Synonyms: DBCCR1L; DBCCR1L1; FAM5C
Tractability: Antibody: UniProt places it where antibodies can reach, with high confidence; UniProt predicts a signal peptide or a membrane-spanning region; its Gene Ontology location is reachable by antibodies, with medium confidence. PROTAC: ubiquitination databases record sites on it.
Gene: Protein-coding gene on chromosome 1 (190,097,658 to 190,478,404, reverse strand). Ensembl gene ENSG00000162670.
Subcellular location: Secreted; Mitochondrion
Gene Ontology:
Biological process: cellular response to retinoic acid; central nervous system neuron differentiation; negative regulation of mitotic cell cycle; negative regulation of cell cycle; nervous system development; positive regulation of neuron differentiation
Cellular component: cytoplasm; dendrite; neuronal cell body; extracellular region; mitochondrion
Genetic constraint (gnomAD): Loss-of-function variants: 16 observed, 66.75 expected, observed/expected ratio (o/e) 0.24, 90% interval 0.16 to 0.36. The upper end of that interval is the gene's LOEUF score, 0.36, which puts it in group 1 of 6, group 1 being the genes least tolerant of losing a copy. Missense variants: 929 observed, 955.02 expected, observed/expected ratio (o/e) 0.97, 90% interval 0.92 to 1.03. Synonymous variants: 374 observed, 344.13 expected, observed/expected ratio (o/e) 1.09, 90% interval 1 to 1.18.
Homologues: Orthologues: chimpanzee BRINP3 (99% identical), macaque BRINP3 (99% identical), dog BRINP3 (99% identical), pig BRINP3 (98% identical), rabbit BRINP3 (98% identical), mouse Brinp3 (98% identical), rat Brinp3 (98% identical), tropical clawed frog brinp3 (90% identical), guinea pig BRINP3 (90% identical), zebrafish brinp3a.2 (76% identical). Paralogues in human: BRINP2 (71% identical), BRINP1 (53% identical).